GLS (glutaminase)
Diseases named in the same sentence as GLS in open-access papers (continued):
Sharing a sentence is not in itself a finding about the gene and the disease.
dementia (3 papers, 2012 to 2020). Loss of intellectual abilities interfering with an individual's social and occupational functions. "The glutaminase C (GAC, one isoform of GLS1) mRNA levels in HIV associated-dementia (HAD) individuals correlate with STAT1 (p<0.01), IFN-α (p<0.05) and IFN-β (p<0.01)." (PMID 22479354, 2012). "The increased glutamate may result from upregulation of glutamate-generating enzyme glutaminase, which are found HIV-infected microglia and macrophages, and are potentiated by interferons from the innate immune responses, as shown in postmortem brain tissues of patients with HIV dementia." (PMID 32758262, 2020).
experimental autoimmune encephalomyelitis (3 papers, 2019 to 2023). An autoimmune demyelinating disease of the central nervous system that is produced experimentally in animals by the injection of homogenized brain or spinal cord in Freund's adjuvant. "The glutaminase antagonist JHU083, a prodrug of DON, has been reported to be a potential anti-inflammatory modulator to reverse experimental autoimmune encephalomyelitis through inhibiting T cells proliferation and activation." (PMID 35663990, 2022).
HCMV infection (3 papers, 2019 to 2024). "Consistently, the enzyme activities of glutaminase (GLS) and glutamate dehydrogenase (GDH) are also elevated upon HCMV infection." (PMID 31319842, 2019). "We next investigated whether GLS enzymatic activity was increased during MNV infection, a phenotype observed during HCMV infections." (PMID 38976719, 2024).
Hepatic steatosis (3 papers, 2022 to 2025). Steatosis is a term used to denote lipid accumulation within hepatocytes. "In addition, hepatic ammonia accumulation underlying Fatty Liver Disease is associated both with impaired liver ureagenesis through downregulation of the expression of UCEs, and augmented hepatic glutaminase activity." (PMID 36589817, 2022). "Moreover, we found that the effects of glutamine on hepatic steatosis depended on glutaminase 1 (GLS1)." (PMID 40936098, 2025). "First, the fractional contribution of gut ammonia production, disturbed urea cycle function, glutamine synthetase expression or enhanced hepatic glutaminase activity contribution to altered ammonia and glutamine homeostasis in the context of Fatty Liver Disease remains to be addressed." (PMID 36589817, 2022). "Furthermore, our group recently showed that augmented hepatic ammoniagenesis via increased glutaminase activity and overexpression of the high activity glutaminase 1 isoenzyme occurs in Fatty Liver Disease." (PMID 36589817, 2022). "Whether Fatty Liver Disease impairs nitrogen metabolism, or if these alterations in ammonia metabolism, ureagenesis ad glutaminase activity occur first and are the root of the appearance or progression of Fatty Liver Disease remains to be uncovered." (PMID 36589817, 2022). "However, to our knowledge the relevance of glutaminase alterations in Kupffer and endothelial cells underlying Fatty Liver Disease has not been specifically addressed." (PMID 36589817, 2022). "Importantly, the overexpression of GLS was detected in steatotic hepatocytes in pre-clinical and clinical samples of Fatty Liver Disease, with its transcriptional regulation still not fully understood." (PMID 36589817, 2022).
Insulin resistance (3 papers, 2022 to 2024). Increased resistance towards insulin, that is, diminished effectiveness of insulin in reducing blood glucose levels. "In this sense, insulin resistance decreases NMDAR1 expression, increases glutamate levels in mice’s hippocampus, and increases glutaminase activity in humans’ liver." (PMID 39595009, 2024).
malignant glioma (3 papers, 2020 to 2023). A grade III or grade IV glioma arising from the central nervous system. "Therefore, there is still an emerging need to test novel metabolism driven strategies that target various aspects of glutamate-glutamine metabolism in malignant gliomas, for instance, the use of a systemic glutaminase treatment." (PMID 32993063, 2020). "In the cytoplasm, glutamine is converted to glutamate by glutaminase isoenzymes 1 and 2 (GLS1 and GLS2), and in malignant gliomas, GLS2 has been reported to be downregulated while GLS1 is expressed." (PMID 37626776, 2023). "In malignant gliomas, GLS-2 is commonly downregulated, but GLS-1 is expressed, being pivotal in glutaminolysis, which in turn is crucial for GBM cell survival and tumor growth." (PMID 32993063, 2020).
Obesity (3 papers, 2023 to 2025). Accumulation of substantial excess body fat. "The expression of glutamine‐metabolizing proteins—such as glutamine synthetase (GLUL) and glutaminase (GLS)—is altered in white adipose tissue from individuals with obesity and is normalized after bariatric surgery." (PMID 40289598, 2025). "Our analyses of human and mouse WAT in obesity revealed that GLS mRNA levels were increased in both sexes compared with relevant control groups." (PMID 39009762, 2024).
pancreatitis (3 papers, 2016 to 2021). Inflammation of the pancreas. "The concern associated with the commercial use of ASNases is its high glutaminase activity, which can cause liver dysfunction, pancreatitis, leucopenia, neurological seizures, and coagulation abnormalities that lead to intracranial thrombosis." (PMID 30842557, 2019). "Glutaminase activity results in reduction of blood glutamine levels which affects the growth of the normal cells and has consequences such as nerve system dysfunction, pancreatitis, immunological interactions and haemostasis abnormalities, among others." (PMID 33737513, 2021).
pulmonary fibrosis (3 papers, 2022 to 2025). Chronic progressive interstitial lung disorder characterized by the replacement of the lung tissue by connective tissue, leading to progressive dyspnea, respiratory failure, or right heart failure. "Arginase inhibitors simultaneously improve vascular function in COPD and enhance antitumor immunity, while nanoparticle-delivered glutaminase blockers attenuate pulmonary fibrosis while curbing cancer progression." (PMID 40963133, 2025). "Inhibiting glutaminase (GLS1) can reduce bleomycin-induced pulmonary fibrosis, indicating that regulating the glutamine metabolism pathway may have therapeutic potential for pulmonary fibrosis." (PMID 40307370, 2025).
Sepsis (3 papers, 2022 to 2025). Sepsis is defined as life-threatening organ dysfunction caused by a dysregulated host response to infection. "The expression of SLC31A1, CD274, ATOX1, MTF1, UBE2D1, DLD, and VEGFA was found to be upregulated, while that of DLST, UBE2D2, COX11, DLAT, GLS, FDX1, and ULK2 were significantly downregulated in patients with sepsis-associated ALI." (PMID 38779731, 2025). "In an experiment simulating LPS‐induced sepsis, the use of glutaminase (GLS) blockers reduced survival rates in septic mice and promoted the shift of macrophages towards an M1 inflammatory state by inhibiting GLS activity in a laboratory setting." (PMID 39601476, 2024).
small cell lung carcinoma (3 papers, 2017 to 2025). Small cell lung cancer (SCLC) is a highly aggressive malignant neoplasm, accounting for 10-15% of lung cancer cases, characterized byrapid growth, and early metastasis. "In small cell lung cancer, phosphoribosyl pyrophosphate amidotransferase (PPAT), a key enzyme of DNPS, can synergize with glutaminase (GLS) to determine the metabolic fate of glutamine within the cell, thereby sustaining DNA replication and tumor cell proliferation." (PMID 40097378, 2025). "Using qRTPCR to assay glutaminase (GLS), an enzyme that catalyzes the hydrolysis of glutamine to glutamate, we have found that the levels were higher in NSCLC but not in small cell lung cancer (SCLC) cells that were resistant to cisplatin." (PMID 28525376, 2017).
steatosis (3 papers, 2022 to 2025). Increased lipid within the cytoplasm of cells. "Inhibitors of hepatic glutaminase 1 (GLS1) reduce NASH steatosis by increasing very low-density lipoprotein export, and inhibiting GLS1 can reduce oxidative stress in NASH." (PMID 35958576, 2022).
acute myocardial infarction (2 papers, 2022 to 2024). Necrosis of the myocardium, as a result of interruption of the blood supply to the area. "In contrast, patients with acute myocardial infarction exhibit decreased levels of LIAS, PDHB, LIPT1, DLAT, and GLS, along with increased MTF1 levels." (PMID 39360273, 2024).
allergic asthma (2 papers, 2022 to 2025). A asthma with a basis in a pathological type I hypersensitivity reaction. "The expression of the rate-limiting enzyme of proline biosynthesis, glutaminase (GLS), is upregulated in trained macrophages in an allergic asthma mouse model with respiratory virus infection and early life allergen sensitization." (PMID 39863828, 2025). "Inhibition of the key enzyme GLS or PYCR suppressed induction of the trained macrophages, and led to completely prevention of allergic asthma in childhood." (PMID 36211408, 2022).
Arthritis (2 papers, 2017 to 2024). Inflammation of a joint. "Therefore, in this study, we used TrkA and Rab7 pharmacological inhibitors to block the NGF signaling during adjuvant-induced arthritis (AIA) to determine the effect of NGF on glutaminase (GLS) levels in DRG neurons and pain behavior in AIA animals." (PMID 38892241, 2024).
astrocytoma (2 papers, 2021 to 2024). "For ICC, a phase 1b clinical trial (NCT03528642) was performed to study the side effects and optimal dose of the glutaminase inhibitor telaglenastat in combination with radiation therapy and temozolomide for treating patients with IDH-mutated astrocytoma." (PMID 39273177, 2024).
autoimmune disorders (2 papers, 2022 to 2025). "Studies of autoimmunity have primarily focused on membrane glutamine transporters such as ACST2 or glutaminases such as Gls1, which is the main topic in this study." (PMID 35211629, 2022).
gastrointestinal stromal tumor (2 papers, 2020 to 2022). "It has to be mentioned that currently there is an ongoing clinical trial with the GLS-1 inhibitor CB-839 for SDH-associated gastrointestinal stromal tumors and non-gastrointestinal stromal tumors." (PMID 32150977, 2020). "The glutaminase inhibitor telaglenastat (CB-839) is currently being studied within the confines of SDH-associated gastrointestinal stromal tumors and non-gastrointestinal stromal tumors as well (NCT02071862)." (PMID 35163370, 2022).
hepatoblastoma (2 papers, 2024). Hepatoblastoma (HB) is a malignant hepatic tumor and is the most common pediatric liver cancer. "The enzyme glutaminase (GLS), often upregulated in hepatoblastoma, catalyzes the conversion of glutamine to glutamate." (PMID 39596558, 2024). "For example, glutaminase (GLS), a key enzyme in glutaminolysis, can be up-regulated by circHMGCS1 in hepatoblastoma cells." (PMID 38662258, 2024).
Hypoglycemia (2 papers, 2024). A decreased concentration of glucose in the blood. "Hypoglycemia caused a corresponding gain or loss of SF-1 control of Ghrh and GLS gene transcription." (PMID 39401164, 2024). "Outcomes show that hypoglycemia elicits a gain of SF-1 inhibitory control of Ghrh and Ghrh-R mRNA profiles as well as loss of stimulatory influence on GLS transcription in VMNdm Ghrh neurons in the female rat." (PMID 39401164, 2024). "Data show that in females, hypoglycemia elicits a gain of SF-1 inhibitory control of VMNdm Ghrh neuron Ghrh and Ghrh-receptor gene profiles and loss of augmentation of glutaminase transcription; SF-1 gene silencing diminished eu- and hypoglycemic patterns of neuronal nitric oxide gene transcription." (PMID 39401164, 2024). "Hypoglycemia augmented or reduced nitric oxide synthase and glutaminase mRNAs, responses that were attenuated by SF-1 gene silencing." (PMID 39024550, 2024). "New results described here reveal that SF-1 suppresses GLS gene expression during eu- or hypoglycemia, and support the view that this transcription factor may mediate hypoglycemic inhibition of this gene profile." (PMID 39024550, 2024).
hypothyroidism (2 papers, 2024). Abnormally low levels of thyroid hormone. "The patient had a history of RCC, splenic and mesenteric vein thrombosis, hyperlipidemia, and hypothyroidism and was previously treated with sunitinib, pazopanib, nivolumab, and an experimental glutaminase inhibitor." (PMID 39168901, 2024). "However, hypothyroidism decreases glutamate release and glutaminase activity in the rat hippocampus and supplementation reduces these effects." (PMID 39595009, 2024).
mesothelioma (2 papers, 2022 to 2025). A usually malignant and aggressive neoplasm of the mesothelium which is often associated with exposure to asbestos. "Similarly, cuproptosis-associated genes including LIAS, LIPT1, PDHB, GLS, and CDKN2A had significant overall survival in Mesothelioma (MESO) (p < 0.05)." (PMID 36105090, 2022).
neonatal encephalopathy (2 papers, 2023 to 2024). "Thus, a loss of function in glutaminase can cause a neurometabolic disorder that leads to lethal early neonatal encephalopathy." (PMID 36980356, 2023).
optic atrophy (2 papers, 2018 to 2024). A disorder characterized by loss of optic nerve fibers. "Glutaminase deficiency caused by duplication in an exon of the GLS gene led to spastic ataxia, optic atrophy, and degenerative disorder with loss of motor and language skills in a young child." (PMID 39559284, 2024). "In summary, through a combination of whole‐genome sequencing, homozygosity mapping and functional studies, we show that GLS knockout is compatible with human life, and causes childhood onset spastic ataxia and optic atrophy." (PMID 29468182, 2018). "However, we clearly show that GLS is not absolutely required for early human development, although complete absence of GLS activity leads to a complex phenotype with aggressive, childhood onset spastic ataxia, and optic atrophy." (PMID 29468182, 2018).
osteoporosis (2 papers, 2021 to 2024). A condition of reduced bone mass, with decreased cortical thickness and a decrease in the number and size of the trabeculae of cancellous bone (but normal chemical composition), resulting in increased fracture incidence. "Another study suggested that miR-200a-3p is highly expressed in the serum of osteoporosis patients, negatively regulating the expression of glutaminase (GLS), which is linked with the osteogenic differentiation of BMSCs, thus hastening osteoporosis progression." (PMID 35011442, 2021). "Interestingly, we have found that with the same dose, route, frequency and duration of administration, both inhibiting GLS by CB-839 and knocking down GLS1 via adenovirus significantly ameliorated OVX-induced bone loss but deteriorated age-related osteoporosis in mice." (PMID 38377021, 2024). "To explore the effects of inhibiting GLS on different primary osteoporosis types in mice, we used CB-839, a potent and selective GLS inhibitor, to suppress GLS activity in vivo." (PMID 38377021, 2024). "We aimed to determine the effects of inhibiting glutaminase (GLS) on two types of primary osteoporosis and elucidate the related metabolism." (PMID 38377021, 2024). "And most importantly, CB-839 is the only GLS inhibitor currently being evaluated in clinical trials for efficacy and safety in a variety of pathological processes known to be driven by glutamine metabolism except osteoporosis." (PMID 38377021, 2024). "Here, our study uncovered the effects of targeting GLS on the progression of primary osteoporosis and provided evidence for glutaminolysis inhibition as a possible strategy for preventing menopause-related osteoporosis but a path should be avoided while treating age-related osteoporosis." (PMID 38377021, 2024). "Therefore, μCT data suggested that both inhibiting GLS via CB-839 and GLS1 knockdown via adenovirus could accelerate the development of osteoporosis in aged mice but prevent that in ovariectomized mice, mainly in the aspect of trabecular bone mass." (PMID 38377021, 2024).
respiratory failure (2 papers, 2015 to 2024). The significant impairment of gas exchange within the lungs resulting in hypoxia, hypercarbia, or both, to the extent that organ tissue perfusion is severely compromised. "first reported DEE 71 in two families with early‐onset neonatal refractory seizures, respiratory failure, structural brain changes, cerebral edema, high glutamine levels in blood, death in early infancy, and exome sequencing revealed biallelic GLS gene mutation." (PMID 39559284, 2024).
serous ovarian cancer (2 papers, 2023 to 2025). "Indeed, the combination of Olaparib with a glutaminase inhibitor (CB-839) led to a six-fold decrease in the IC50 of the drug for a BRAC2-deficient high-grade serous ovarian cancers cell line, whereas monotherapy with CB-839 led to only slight sensitivity." (PMID 40507333, 2025).
soft tissue sarcoma (2 papers, 2020 to 2022). A malignant neoplasm arising from muscle tissue, adipose tissue, blood vessels, fibrous tissue, or other supportive tissues excluding the bones. "A recent metabolomics study tested the effect of GLS inhibition with CB-839 in undifferentiated pleomorphic sarcoma (UPS) and soft tissue sarcomas and found that GLS inhibition causes tumor cell death." (PMID 36276057, 2022). "Recent studies have also demonstrated success in therapeutically targeting GLS in cell line and murine models of soft tissue sarcomas." (PMID 36276057, 2022). "Here, the authors show that soft tissue sarcomas expressing high levels of glutaminase (GLS) are particularly sensitive to glutamine starvation and GLS inhibition in tumour-bearing allograft and autochthonous mouse models." (PMID 31980651, 2020).
squamous cell carcinoma (2 papers, 2019 to 2021). A carcinoma arising from squamous epithelial cells. "Also, GLS mRNA level was higher in adenocarcinomas than squamous cell carcinomas (P < 0.001)." (PMID 31668020, 2019).
undifferentiated pleomorphic sarcoma (2 papers, 2020 to 2022). An undifferentiated soft tissue sarcoma characterized by the presence of a pleomorphic malignant cellular infiltrate. "In contrast to previous studies, treatment of autochthonous tumour-bearing animals with Telaglenastat (CB-839), an orally bioavailable GLS inhibitor, successfully inhibits undifferentiated pleomorphic sarcoma (UPS) tumour growth." (PMID 31980651, 2020).
Acidosis (1 paper, 2018). Abnormal acid accumulation or depletion of base. "Metabolic acidosis results in the upregulation of enzymes which direct the metabolism of glutamine towards ammoniagensis (GLS and glutamate dehydrogenase 1) and gluconeogenesis (PEPCK)." (PMID 29618784, 2018).
acute leukemia (1 paper, 2016). A clonal (malignant) hematopoietic disorder with an acute onset, affecting the bone marrow and the peripheral blood. "To functionally characterize the importance of Gln for proliferation and survival of AML cells, we next examined the effects of Gln withdrawal or pharmacological inhibition of glutaminase on cellular growth in a panel of acute leukemia cell lines." (PMID 27806325, 2016).
adenovirus infection (1 paper, 2015). "Our proof-of-principle results demonstrate that CB-839-mediated inhibition of GLS activity could potentially be useful to combat adenovirus infection as well as infection by other pathogenic viruses that rely on GLS activity for viral propagation." (PMID 26561297, 2015). "Together, our data support MYC activation-dependent regulation of glutamine metabolism during adenovirus infection through repression of miR-23 leading to upregulation of GLS, as well as MYC-dependent upregulation of the glutamine transporters, ASCT2 and LAT1." (PMID 26561297, 2015).
alcoholic liver diseases (1 paper, 2025). A disorder caused by damage to the liver parenchyma due to alcohol consumption. "Our study reveals a previously unrecognized regulatory mechanism in which glutaminase 1 (GLS1) modulates RNA polymerase II activity, providing a molecular foundation for understanding the hepatoprotective effects of a high‐protein diet in alcoholic liver disease (AFLD)." (PMID 40936098, 2025).